TKT (transketolase)
Diseases named in the same sentence as TKT in open-access papers (continued):
Sharing a sentence is not in itself a finding about the gene and the disease.
Hepatic steatosis (2 papers, 2020 to 2022). Steatosis is a term used to denote lipid accumulation within hepatocytes. "TKT deficiency reduces cell proliferation, increases apoptosis, and alleviates hepatic steatosis and fibrosis." (PMID 36314067, 2022). "Loss of TKT in the liver increased apoptosis, reduced cell proliferation, decreased TNF-α, IL-6, and STAT3 levels, and alleviated DEN/HFD-induced hepatic steatosis and fibrosis, highlighting a key role for TKT in promoting genome instability during liver injury and tumor initiation." (PMID 32913470, 2020).
Insulin resistance (2 papers, 2012 to 2024). Increased resistance towards insulin, that is, diminished effectiveness of insulin in reducing blood glucose levels. "In this study, rats fed the high-fructose diet developed insulin resistance and hyperinsulinemia, which did not affect erythrocytes transketolase activity." (PMID 23065486, 2012).
liver disease (2 papers, 2015 to 2020). "While deficiency of other PPP enzymes, such as transketolase (TKT), are incompatible with mammalian cell survival, mice lacking TAL are viable and develop progressive liver disease attributed to oxidative stress." (PMID 31769880, 2020).
malnutrition (2 papers, 2020 to 2021). Inadequate nutrition resulting from poor diet, malabsorption, or abnormal nutrient distribution. "Reduced erythrocyte transketolase activity is likely a result of malnutrition rather than a refeeding complication, and does not necessarily infer reduced levels of thiamine." (PMID 32884809, 2020).
Nephropathy (2 papers, 2021 to 2024). A nonspecific term referring to disease or damage of the kidneys. "The results indicated that the transketolase SNP rs11130362 and the fructosamine 3-kinase SNP rs1056534 together had a significant effect on nephropathy progression (p = 0.00645)." (PMID 38928135, 2024).
oral cancer (2 papers, 2014 to 2021). "UM1 and UM2 oral cancer cells were transfected with siRNA to transketolase (TKT) or siRNA to adenylate kinase (AK2), and Western blotting was used to confirm the knockdown." (PMID 24666435, 2014). "In this study, we have demonstrated that the knockdown of TKT or AK2 expression significantly inhibits the proliferation of oral cancer cells." (PMID 24666435, 2014). "To investigate if TKT is abnormally expressed in oral cancer cells, we compared the endogenous expression levels of TKT among NHOKs, UM1 and UM2 cell lines." (PMID 24666435, 2014). "Our study demonstrates that siRNA knockdown of endogenous TKT expression significantly impairs the proliferation of the UM1 and UM2 oral cancer cells." (PMID 24666435, 2014). "siRNA silencing of TKT or AK2 was performed on UM1 and UM2 oral cancer cells, which were both derived from a same tongue squamous cell carcinoma, and the effects of their inhibition on cell proliferation, cellular uptake of glucose and glutamine and lactate production were investigated." (PMID 24666435, 2014).
pancreatic ductal adenocarcinoma (2 papers, 2023 to 2025). An infiltrating adenocarcinoma that arises from the epithelial cells of the pancreas. "In pancreatic ductal adenocarcinoma, S100A11 bound to SMYD3 and then activated the expression of transketolase (TKT), thus stimulating pentose phosphate pathway to aggregate the malignant phenotypes." (PMID 37386026, 2023). "MiR-3663-5p can directly target TKT to diminish the nucleotide synthesis of the PPP pathway, thereby increasing gemcitabine sensitivity, which may be a supplement to chemotherapy advantages in pancreatic ductal adenocarcinoma." (PMID 40227333, 2025).
prostate carcinoma (2 papers, 2021 to 2025). A carcinoma that arises from epithelial cells of the prostate gland. "Cancer cells increase their expression of TKT and TALDO to accelerate the nonoxidative branch of the PPP, with elevated levels of TKT reported in lung, breast, and prostate cancer cells, and elevated levels of TALDO reported in gastric adenocarcinoma." (PMID 33946927, 2021).
renal carcinoma (2 papers, 2008 to 2025). A carcinoma arising from the epithelium of the renal parenchyma or the renal pelvis. "In summary, our findings reveal that TKT collaborates with PKM2 to drive renal cancer metastasis by enhancing cell migration and invasion." (PMID 41253799, 2025). "Conversely, upon overexpressing PKM2 in renal cancer cells with stable TKT knockdown, we observed that such overexpression reversed the TKT knockdown-induced metabolic alterations, leading to elevated glucose uptake, lactate production, and ATP levels." (PMID 41253799, 2025). "The results showed that TKT knockdown in 786-O and ACHN cells significantly inhibited RCC cell proliferation, while TKT overexpression markedly enhanced renal carcinoma cell proliferation." (PMID 41253799, 2025). "Further, with renal cancer another carcinoma displayed intensively elevated transketolase activity due to TKTL1-upregulation." (PMID 18700018, 2008).
schizophrenia (2 papers, 2017 to 2025). A major psychotic disorder characterized by abnormalities in the perception or expression of reality. "The schizophrenia susceptibility genes detected in inh-PVALB neurons in the midbrain included genes such as DGKZ, INPP4B and TKT." (PMID 39397771, 2025).
wet beriberi (2 papers, 2011 to 2018). "Furthermore, measurements of serum thiamine concentration, the TPP effect and erythrocyte transketolase activity were the most common methods used, especially the measurement of thiamine concentration, in documents discussing the diagnosis of wet beriberi." (PMID 29489643, 2018).
adenoma (1 paper, 2017). A neoplasm arising from the epithelium. "TKT expression was higher in hyperplastic lesions and in both benign and malignant tumors compared to the normal mammary gland, while TKTL1 levels were remarkably higher in hyperplastic lesions, simple adenomas and simple carcinomas than in the normal mammary glands (P < 0.05)." (PMID 28143530, 2017).
AIDS (1 paper, 2024). A syndrome resulting from the acquired deficiency of cellular immunity caused by the human immunodeficiency virus (HIV). "Reduced expression and activity of TKT, a thiamine dependent enzyme, depletes NADPH, disrupts programmed cell death, and contributes to cancer, neurodegenerative diseases, and AIDS pathologies by affecting T-cell eradication." (PMID 38427142, 2024).
anthrax (1 paper, 2007). "The main immunogenic proteins detected by 2-DE Western blot analysis using sera from humans infected with cutaneous anthrax include the 83 and 63 kDa charge variants of protective antigen (PA), followed by charge variants of enolase and transketolase." (PMID 17662140, 2007).
autoimmune disease (1 paper, 2025). A disorder resulting from loss of function or tissue destruction of an organ or multiple organs, arising from humoral or cellular immune responses of the individual to their own tissue constituents. "However, deletion of the enzyme transketolase (TKT) in mice induces impaired Treg suppressive function, despite normal FoxP3 expression levels and leads to unhampered oxidative phosphorylation causing fatal autoimmune disease." (PMID 40963621, 2025).
brucellosis (1 paper, 2025). Brucellosis is a bacterial infection that spreads from animals to people via unpasteurized dairy products or by exposure to contaminated animal products or infected animals. "Consequently, we harnessed the genetic resistance to brucellosis in goats by modulating the expression of the TKT, RPIA and AMPD genes." (PMID 39825331, 2025).
chronic kidney disease (1 paper, 2014). Impairment of the renal function secondary to chronic kidney damage persisting for three or more months. "A study that evaluated thiamine status in patients with stage 4 and stage 5 chronic kidney disease revealed that a substantial proportion of these patients had a high erythrocyte transketolase activity indicating a thiamine deficient state." (PMID 25105030, 2014).
chronic myeloid leukemia (1 paper, 2025). "The combination of imatinib (Gleevec, STI571) and the TKT inhibitor oxythiamine (OT) re-established the sensitivity of chronic myeloid leukemia cells to imatinib." (PMID 40227333, 2025).
colon adenocarcinoma (1 paper, 2022). "By bioinformatic analysis in TIMER2.0, we found that TKT is a low-frequency mutated gene (1.4%) in human colon adenocarcinoma." (PMID 35280908, 2022). "As TKT was up-regulated in colon adenocarcinoma, we evaluated the correlation of TKT expression and prognosis in human colon adenocarcinoma." (PMID 35280908, 2022). "TKT expression was examined in the human colon adenocarcinoma tissue microarray and xenografts." (PMID 35280908, 2022).
depression (1 paper, 2024). "The five hub genes, RNF24, MGAM, FOS, and TKT, were deemed potential diagnostic and prognostic markers for patients with pain–depression comorbidity." (PMID 39125922, 2024). "As a result, we discovered 43 key genes associated with pain–depression comorbidity, along with the identification of RNF24, MGAM, FOS, TKT, and SIGLEC5 as hub genes." (PMID 39125922, 2024).
developmental delays (1 paper, 2025). "Finally, recessively inherited pathogenic alleles in TKT have been reported to be associated with short stature, developmental delays, and congenital heart defects (OMIM 617044)." (PMID 40525707, 2025).
diabetic neuropathy (1 paper, 2024). A chronic, pathological complication associated with diabetes mellitus, where nerve damages are incurred due to diabetic microvascular injury involving small blood vessels that supply these nerves, resulting in peripheral and/or autonomic nerve dysfunction. "In the future, the parameters of the thiamine metabolism should be measured to explore a possible genotype–phenotype interaction between the latter and transketolase SNPs in relation to diabetic neuropathy." (PMID 38928135, 2024). "As well, as the cross-sectional study design did not allow for the determination of the predictive value of transketolase SNPs on the development and progression of diabetic neuropathy, which has to be verified in long-term prospective studies." (PMID 38928135, 2024).
enteritis (1 paper, 2025). Inflammation of the small intestine. "Indeed, studies have shown that TKT deficiency disrupts the normal function of the intestinal barrier, which in turn leads to enteritis." (PMID 40230848, 2025).
esophageal tumor (1 paper, 2024). "Single-cell RNA sequencing results also showed that TKT was highly expressed in epithelial tumor tissues of ESCC, whereas G6PD, a rate-limiting enzyme in the oxidative PPP, was only weakly expressed in esophageal tumor tissues." (PMID 39080260, 2024).
HIV-1 infection (1 paper, 2019). The type species of lentivirus and the etiologic agent of acquired immunodeficiency syndrome (AIDS). "Furthermore, the abundance of TKT RNA measured by microarrays in human lymphatic tissue was significantly increased in stage-specific patterns of HIV-1 infection [iFigure/GSE16363]." (PMID 31415630, 2019).
inflammatory bowel disease (1 paper, 2021). A spectrum of small and large bowel inflammatory diseases of unknown etiology. "Inflammatory bowel disease (IBD) has a close association with transketolase (TKT) that links glycolysis and the pentose phosphate pathway (PPP)." (PMID 34535624, 2021).
kidney cancer (1 paper, 2025). Primary or metastatic malignant neoplasm involving the kidney. "Through an analysis of data from the TCGA database, we observed that TKT was not only highly expressed in tumor tissues from kidney cancer patients, but also exhibited a negative correlation with patient survival." (PMID 41253799, 2025).
lactic acidosis (1 paper, 2013). Metabolic acidosis characterized by the accumulation of lactate in the body. "Analysis of the microarray data for all the KEGG-listed PPP genes indicated that lactic acidosis induced the expression of G6PD, TKT and triose phosphate isomerase (TPI)." (PMID 24359630, 2013).
leishmaniasis (1 paper, 2018). Infectious disease that is transmitted through the bite of hematophagous female phlebotomine sand flies. "TKT therefore offers a potential target for new drugs aimed at treating leishmaniasis, although there will be a time lag before suitable inhibitors are available for testing." (PMID 29554142, 2018). "Crucially, mice inoculated with the TKT knock-out parasites did not develop an infection pointing to the enzyme playing a key role in allowing the parasites to remain viable in the host, indicating that TKT may be considered a useful target for development of new drugs against leishmaniasis." (PMID 29554142, 2018).
multiple sclerosis (1 paper, 2022). A progressive autoimmune disorder affecting the central nervous system resulting in demyelination. "Finally, transketolase is immunogenic in multiple sclerosis." (PMID 35027076, 2022).
pancreatic adenocarcinoma (1 paper, 2014). "Transketolase inhibitors have been shown to reduce the rate of proliferation of pancreatic adenocarcinoma cells in culture while, conversely, stimulating transketolase activity in cancer cells using thiamine promoted tumor growth in mice." (PMID 25188286, 2014).
renal cell carcinoma (1 paper, 2009). "Langbein demonstrated that Transketolase was more elevated in metastasizing renal cell cancer and TKTL1 protein was significantly overexpressed in progressing renal cell cancer." (PMID 19331662, 2009).
Sepsis (1 paper, 2019). Sepsis is defined as life-threatening organ dysfunction caused by a dysregulated host response to infection. "Combined treatments with a TKT inhibitor and vitamin B1 may thus pave the way to an alternative therapeutic regime and recommendation for adverse pathological outcomes involving excessive NET formation such as in severe sepsis or auto-inflammatory diseases." (PMID 31415630, 2019).
steatosis (1 paper, 2016). Increased lipid within the cytoplasm of cells. "The transketolase levels were especially low in rats with steatosis, probably due to the damage to mitochondria and peroxisomes caused by lipid peroxidation products." (PMID 27792191, 2016). "In rats with steatosis the relative abundance of transketolase was significantly reduced in comparison with the N and HL groups, whereas the relative abundance of PRPs was significantly increased in HA, more than in HL." (PMID 27792191, 2016).
Stroke (1 paper, 2026). Sudden impairment of blood flow to a part of the brain due to occlusion or rupture of an artery to the brain. "In contrast, SLC16A1, SIRT3, PFKP, and TKT were inversely associated with stroke risk, suggesting a potential protective role." (PMID 41877258, 2026).
cancer (123 papers, 2006 to 2025). A tumor composed of atypical neoplastic, often pleomorphic cells that invade other tissues. "TKT, a crucial host gene encoding an enzyme (transketolase) that maintains ATP production in gut epithelium and an important regulator of cancer, responded to B. adolescentis." (PMID 41278623, 2025). "TKT was identified as a high-risk factor in most cancers, particularly KICH, where it exhibited the highest HR (4.756), suggesting that elevated TKT expression dramatically increased the risk of mortality in these patients." (PMID 40230848, 2025). "The role of TKT in different cancers demonstrates its dual role as both a potential risk factor and a protective factor, a phenomenon that highlights the complexity of its function." (PMID 40230848, 2025). "Although there is growing evidence showing that TKT promotes the progression of various cancers, the specific biological mechanisms underlying the function of TKT remain incompletely understood." (PMID 39080260, 2024). "Several studies had been performed to determine the associations between the TKT genes family and cancer carcinogenesis 15-18." (PMID 35711845, 2022). "TKT was upregulated at protein levels in cancer compared with normal tissues (P <0.05), and high TKT expression was associated with advanced tumor stage in our cohorts." (PMID 35711845, 2022). "Although accumulating evidence has confirmed that TKT promotes the proliferation and migration of various cancer cells, the specific biological mechanisms underlying the regulation of TKT mediated by S100A11 remain incompletely understood." (PMID 35752610, 2022). "Numerous studies have implicated the role of transketolase in the pathogenesis of neurodegenerative diseases, diabetes, and cancer." (PMID 29208764, 2018). "Thiamine supplementation has been shown to increase tumor proliferation in vitro through transketolase activation, and multiple studies have linked thiamine metabolism to cancer through numerous mechanisms." (PMID 26942765, 2016). "The protein expression pattern in three clusters suggested that metabolic dynamic changes (dynamic changes of transketolase activity) in MIA cancer cells in response to OT treatment caused dynamic changes of cellular protein signals." (PMID 23890079, 2013). "A number of our previous studies have shown that inhibition of activity of either transketolase in the pentose phosphate cycle, or glycogen phosphorylase causes cell cycle arrest leading to cancer cell apoptosis." (PMID 23890079, 2013). "Our analysis of HCC using the TCGA database confirmed the correlation of TKT with additional ICP genes, including CD44, CD80, CD86, and CTLA-4, which may explain the association of TKT overexpression with poorer prognoses in patients with cancer." (PMID 40230848, 2025). "The enrichment of pathways related to DNA replication and the cell cycle suggests that TKT expression may drive increased proliferative activity in tumor cells, promoting uncontrolled cell division—a hallmark of cancer." (PMID 40230848, 2025). "Exosomes from both the cell lines contained G6PD, transketolase and transaldolase 1 which are part of the pentose phosphate pathway and may be diagnostic of late stage cancer." (PMID 29262670, 2017). "Human TKT has attracted considerable attention as it was implicated in several pathological disorders such as the Wernicke-Korsakoff Syndrome, Alzheimer’s disease, diabetes and cancer." (PMID 23118983, 2012). "In our previous study, we generated a liver-specific TKT knockout mouse strain, we found a novel role of TKT in increasing genome instability by limiting de novo nucleotide biosynthesis, and loss of the enzyme significantly reduced liver injury and cancer initiation." (PMID 31949131, 2020). "Given STAT3’s established role in modulating glucose metabolism, this regulation suggests a direct link between STAT3 and TKT in cancer cell metabolism reprogramming." (PMID 40230848, 2025).